KAT2A (lysine acetyltransferase 2A)
Diseases named in the same sentence as KAT2A in open-access papers (continued):
Sharing a sentence is not in itself a finding about the gene and the disease.
leukemia (continued). "Besides, KAT2A has been reported to promote stem-like cell propagation in leukemia and regulate the resistance to tamoxifen in breast cancer." (PMID 38168564, 2024). "Minimising heterogeneity favours the propagation of leukaemia stem cells; therefore, the authors knocked out Kat2a in leukaemia stem cells, which enhanced variability of transcription at certain loci and shifted the cell state from self-renewal to differentiation." (PMID 39560103, 2024). "In contrast, excision of Kat2a in RT1(9a) cells after in vitro transformation by three rounds of serial replating led to a reduction in colony formation, suggesting that Kat2a loss favors leukemia development only at a preleukemia stage." (PMID 35921412, 2022). "Analysis of the impact of Kat2a target programs in other malignant and normal stem cell systems, or at different stages of leukemia progression will test this hypothesis." (PMID 31985402, 2020). "Having established that Kat2a can control the H3K9ac status, and putatively TF binding, of a subset of promoters, with impact on their bursting activity, we focused on the nature of the genes showing reduced frequency of bursting in Kat2a KO leukemias." (PMID 31985402, 2020). "(B) Gene expression CV in Kat2a WT and KO primary leukemia cells." (PMID 31985402, 2020). "Importantly, we demonstrated that Kat2a-depleted leukemia stem-like cells (phenotypic L-GMP) have reduced protein synthesis activity, putatively due to a perturbation of polysomal assembly consequent to variability in levels of ribosomal proteins." (PMID 31985402, 2020). "(D) Pair-wise distance measure between any two genes across Kat2a-WT and KO primary leukemia cells." (PMID 31985402, 2020). "Although we cannot exclude that serial or competitive transplantation may reveal a defect in Kat2a KO HSC, our data are nevertheless supportive of a difference in the sensitivity of leukemia cells to Kat2a loss." (PMID 31985402, 2020). "We thus suggest that Kat2a acts through co-option of the transcriptional machinery present at target loci, rather than rely on a unique conserved transcription factor circuit, to exert its pleiotropic activating effects in leukemia cells." (PMID 31985402, 2020). "(C) Flow cytometry analysis of BM cellularity of primary Kat2a WT or KO leukemias: shown are late (Mac1+Gr1+) and early (Mac1+Gr1-) differentiated populations and Gr1-Mac1-cKit+Sca1-CD34+FcgR+ candidate stem-like L-GMP cells, mean ± SEM, n = 4–5; 2-tailed t-test performed." (PMID 31985402, 2020). "In this light, we asked if its enhancement in Kat2a KO leukemias resulted in an imbalance of self-renewal vs differentiation states that could lead to the observed delay in leukemia progression." (PMID 31985402, 2020). "Additionally, KAT2A knock-out in leukemia stem-like cells lost repopulating capacity." (PMID 35681732, 2022). "We next tested the impact of Kat2a loss on the preleukemia model driven by the exon 9a splicing variant of the RUNX1-RUNX1T1[RT1(9a)] fusion gene, which, when retrovirally delivered to adult BM cells, leads to long-latency, incomplete-penetrance leukemia in irradiated recipients." (PMID 35921412, 2022). "Importantly, the level of locus excision was mildly increased during transformation, indicating that loss of Kat2a does not impede the initial selection of leukemia-transformed clones." (PMID 31985402, 2020). "Additionally, we could observe an enrichment of translation-associated gene expression signatures amongst undifferentiated cells relatively depleted in Kat2a KO leukemias, suggesting that they may contribute to leukemia propagation and/or maintenance." (PMID 31985402, 2020). "Targeting the GCN5 family H3K9 acetyltransferases (including KAT2A and KAT2B) in the mammalian genome, thus represents a promising strategy for leukemia therapy." (PMID 38394203, 2024).
leukemia (continued). "Nonetheless, our study revealed a compensatory relationship between KAT2A and KAT2B in maintaining H3K9ac, allowing leukemia cells to escape the single KAT2 gene targeting." (PMID 38394203, 2024). "(F) ChIP-quantitative PCR analysis of Gabpa binding in selected Kat2a acetylation target promoter peaks; mean values for two independent experiments using pooled BM of Kat2a WT vs KO MLL-AF9 secondary leukemias." (PMID 31985402, 2020). "Moreover, perturbation of the translational machinery could re-capture the enhanced in vitro differentiation of leukemia cells observed upon Kat2a depletion, suggesting that alterations in protein synthesis activity may indeed be central to exit from leukemia self-renewal." (PMID 31985402, 2020). "(E) ChIP-quantitative PCR analysis of Myc binding in selected Kat2a acetylation target promoter peaks; mean values for 2–4 independent experiments using pooled BM or Spleen of Kat2a WT vs KO MLL-AF9 secondary leukemias." (PMID 31985402, 2020). "(A) Quantification of H3K9ac and H3K27ac ChIPseq peaks at H3K4me3 gene promoters in Kat2a WT and KO primary MLL-AF9 leukemias." (PMID 31985402, 2020). "Our results propose that KAT2A inhibition should be investigated as a therapeutic strategy in AML and provide a large number of genetic vulnerabilities of this leukemia that can be pursued in downstream studies." (PMID 27760321, 2016). "By reviewing the analysis of KAT2A-depleted pre-leukaemia and leukaemia models, I discuss that the net result of transcriptional noise is diversification of cell fates secondary to alternative transcriptional programmes." (PMID 38432321, 2024). "We found that depletion of either Kat2a or Kat2b individually minimally affected the cellular survival (red and green populations), H3K9ac level, and the LSC marker c-Kit expression (red and green groups) in the leukemia cells." (PMID 38394203, 2024). "(C) Binned gene expression CV across the distribution of gene expression averages for Kat2a WT and KO primary leukemia cells, KS non-parametric test, p-value<0.05 for all bins." (PMID 31985402, 2020). "In this study, we combine functional assays with single-cell transcriptional analysis and identify a requirement for the histone acetyl-transferase Kat2a in sustaining leukemia stem-like cells (LSC) and their downstream leukemia cellular structure in MLL-AF9-initiated AML." (PMID 31985402, 2020). "To this end, we pooled samples from 4 to 5 primary leukemias of each genotype, sorted live GFP+ cells reporting the presence of the MLL-AF9 fusion, and successfully sequenced over 4000 cells Kat2a WT and KO cells each, for a total of 13166 transcripts, using a high-throughput 10X Genomics platform." (PMID 31985402, 2020). "Altogether, the data suggest that phenotypic leukemia stem-like cells are less translationally active in the absence of Kat2a, which could explain their reduced functionality." (PMID 31985402, 2020). "Indeed, cluster seven scores as the most stem-like transcriptional state, suggesting that Kat2a KO leukemias may be depleted of functional, if not surface phenotype, LSC." (PMID 31985402, 2020). "Alternatively, the lack of association could reflect the fact that our subset of acetylation targets captures absolute, but not relative losses of promoter H3K9ac upon Kat2a KO, as a result of the necessarily limited replication of ChIP analysis of primary leukemia cells." (PMID 31985402, 2020). "This suggests that Kat2a-mediated maintenance of LSC may be achieved through general, rather than leukemia-specific, regulatory programs, with putative implications for other leukemic and non-leukemic malignancies." (PMID 31985402, 2020).
gastric cancer (10 papers, 2017 to 2022). A primary or metastatic malignant neoplasm involving the stomach. "Gastric cancer-associated WDR5 and KAT2A binding lncRNA (GCAWKR) modulates the affinity for WDR5/KAT2A complexes in the promoter region of target genes." (PMID 32429086, 2020). "GClnc1 acts as a modular scaffold for WDR5 (WD repeat domain 5) and KAT2A (Lysine Acetyltransferase 2A) to specify the histone modification pattern, thus promoting gastric cancer cell proliferation and invasiveness." (PMID 29970131, 2018). "Another study demonstrated that gastric cancer-associated lncRNA1 (GClnc1) could act as a scaffold lncRNA linking WDR5 and KAT2A, triggering proliferation, invasion and metastasis by activating SOD2 in GC." (PMID 36419649, 2022). "Previous work has shown that the lncRNAs GClnc1 and GCAWKR can serve as scaffolds for KAT2A and WDR5 in gastric cancer, and can thereby serve as positive regulators of this enzyme." (PMID 31320749, 2020). "Previous studies have revealed that the KAT family protein KAT2A can bind to the lncRNAs GClnc1 and PVT1 in gastric cancer and NPC, respectively." (PMID 33330099, 2020). "Mechanistically, GClnc1 binds to WDR5 and KAT2A histone acetyltransferase, acts as a modular scaffold of WDR5 and KAT2A complexes, coordinates their localization and consequently alters gastric cancer proliferation, migration and invasion." (PMID 29113415, 2017).
acute myeloid leukemia (9 papers, 2020 to 2025). Acute myeloid leukemia (AML) is a group of neoplasms arising from precursor cells committed to the myeloid cell-line differentiation. "Among these genes, KAT2A was recently identified as a vulnerability in some forms of acute myeloid leukemia." (PMID 37763801, 2023). "In previous studies, KAT2A has been shown to be a viable target for reducing the growth of acute myeloid leukemia by significantly promoting myeloid differentiation and apoptosis." (PMID 37789275, 2023). "Previous studies have indicated that KAT2A is an essential candidate, and targeting KAT2A could significantly induce myeloid differentiation and apoptosis to suppress the tumor growth of acute myeloid leukemia (AML)." (PMID 34268311, 2021). "In the future, it may be possible to develop drugs that target human KAT2A to treat acute myeloid leukaemia." (PMID 31985402, 2020). "CRISPR/Cas9 screening platform have been used to identify genetic vulnerabilities in acute myeloid leukemia (AML) cells, including several established (such as DOT1L, BCL2, and MEN1) and novel (such as KAT2A) therapeutic targets for AML." (PMID 39696697, 2024). "Acute Myeloid Leukemia (AML) cell lines such as MOLM-13, MV4-11, HL-60, OCI-AML2, OCI-AML3 were examined for therapeutic targets via genome-wide CRISPR screening, indicating KAT2A inhibition as a therapeutic strategy in AML." (PMID 38816739, 2024).
pancreatic cancer (8 papers, 2021 to 2025). "Nine genes, including KAT2A, were highly expressed in pancreatic cancer and were associated with poor prognosis." (PMID 35422864, 2022). "For instance, KAT2A-mediated H3K79 succinylation in the promoter of YWHAZ (encoding 14-3-3zeta expression) is essential for β-catenin stability to promote pancreatic carcinoma metastasis." (PMID 35449131, 2022). "In pancreatic cancer, high KAT2A levels have been linked to adverse clinical outcomes." (PMID 41225436, 2025). "High KAT2A expression was associated with a poorer prognosis in pancreatic cancer." (PMID 35422864, 2022). "KAT2A was highly expressed in pancreatic cancer; its mediated expression of 14-3-3ζ and β-catenin has been shown to promote glycolysis, proliferation, epithelial-mesenchymal transition, and migration in pancreatic cancer cells." (PMID 35422864, 2022). "Increasing studies have already indicated that KAT2A was an epigenetic oncogene in various cancers, like pancreatic carcinoma, gastric carcinogenesis, and nasopharyngeal carcinoma." (PMID 34268311, 2021). "Additional evidence from pancreatic cancer models demonstrates that KAT2A facilitates malignant progression through mechanisms involving enhanced proliferation, migratory capacity, invasive potential, epithelial-mesenchymal transition, and metabolic reprogramming." (PMID 41225436, 2025). "In addtrion, KAT2A-mediated histone succinylation was recently found to play a new role in the regulation of gene expression and β-catenin stability to promote tumor cell proliferation and invasion of pancreatic carcinoma cells." (PMID 37047552, 2023). "Besides, KAT2A mediates the H3K79 succinylation to modulate β-catenin stability and aggravate the progression of pancreatic cancer." (PMID 37415153, 2023). "As a key downstream gene of KAT2A and E2F1, we also found that UBE2C significantly inhibited the proliferation of the liver cancer cell line, HepG2, and pancreatic cancer cell line, BxPC3, through a CCK-8 assay, which suggested that UBE2C plays a critical role in pan-cancer." (PMID 36292703, 2022).
nasopharyngeal carcinoma (6 papers, 2020 to 2024). A carcinoma arising from the nasopharyngeal epithelium. "The activation of KAT2A can promote nasopharyngeal carcinoma cell proliferation 40 and lung cancer cell apoptosis." (PMID 32742447, 2020). "Similarly, high expression of KAT2A promotes the proliferation of nasopharyngeal carcinoma cells." (PMID 38835015, 2024). "KAT2A recruited a nuclear receptor binding protein TIF1β by mediating H3K9 acetylation to activate NF90-maintained HIF1α stability, further enhancing nasopharyngeal carcinoma progression." (PMID 35449131, 2022). "In nasopharyngeal cancer, lncRNA PVT1 can act as a scaffold for the chromatin modifier KAT2A, recruiting the nuclear receptor-binding protein TIF1β to activate NF90 transcription, thereby increasing HIF-1α and upregulating radioresistance." (PMID 35600868, 2022).
glioma (5 papers, 2021 to 2025). A benign or malignant brain and spinal cord tumor that arises from glial cells (astrocytes, oligodendrocytes, ependymal cells). "For example, it was revealed that high KAT2A expression is associated with poor prognosis in breast, lung and colon cancers; however, it is associated with good prognosis in pancreatic adenocarcinoma and glioma." (PMID 35681732, 2022). "In contrast, KAT2A protein was overexpressed and positively correlated with tumor size in human glioma and non-small-cell lung carcinoma (NSCLC)." (PMID 34149798, 2021). "For example, OGDH directly binds the histone acetyltransferase KAT2A and generates succinyl-CoA, which is used by KAT2A to succinylate H3K79, and enhance transcription and tumor proliferation in glioma and HEK293 cell lines." (PMID 36299478, 2022).
hepatocellular carcinoma (5 papers, 2020 to 2025). A malignant tumor that arises from hepatocytes. "This diagnostic utility parallels previously documented findings demonstrating KAT2A’s value as a diagnostic indicator in hepatocellular carcinoma." (PMID 41225436, 2025). "Furthermore, functional studies in hepatocellular carcinoma reveal KAT2A’s involvement in suppressing tumor cell proliferation, inducing G1 phase cell cycle arrest, and promoting apoptotic pathways." (PMID 41225436, 2025). "The lncRNA NEAT1 also interacts with KAT2A to promote deterioration of hepatocellular carcinoma." (PMID 31320749, 2020). "In glioblastoma, KAT2A/α-KGDH complex-driven histone H3 succinylation at K79 activates oncogenic transcription, while in hepatocellular carcinoma, OXCT1-succinylated LACTB reinforces mitochondrial metabolism to support tumor progression." (PMID 41383634, 2025).
colon cancer (4 papers, 2018 to 2025). "Reduction in the expression of HDAC3, P300/CBP-associated factor (PCAF) and lysine acetyltransferase 2A (KAT2A/GCN5) weaken the repair mechanism of colon cancer cells." (PMID 30445746, 2018).
colorectal cancer (4 papers, 2023 to 2025). A primary or metastatic malignant neoplasm that affects the colon or rectum. "In colorectal cancer (CRC), increased KAT2A expression is associated with a more aggressive phenotype." (PMID 40140561, 2025). "In colorectal cancer, KAT2A overexpression has been shown to enhance cell proliferation, migration, invasion capabilities, and glycolytic metabolism." (PMID 41225436, 2025). "KAT2A has been reported to promote carcinogenesis in colorectal cancer by interacting with RNA-binding protein PTBP1 and to modulate cGAS through increasing expression and post-translational modification in systemic lupus erythematosus." (PMID 37047552, 2023). "KAT2A, a histone acetyltransferase, promotes cell proliferation and invasion by acetylating H3K9 and activating E2F1 in colorectal cancer." (PMID 40949882, 2025).
prostate carcinoma (4 papers, 2017 to 2025). A carcinoma that arises from epithelial cells of the prostate gland. "In this study, we found that KAT2A expression was increased in abiraterone-resistant prostate cancer C4-2 cells (C4-2-AbiR)." (PMID 34381019, 2021). "Consistently, elevated expression of KAT2A was observed in patients with prostate cancer exhibiting high-grade disease or biochemical recurrence following radical prostatectomy, as well as in those with poor clinical survival outcomes." (PMID 34381019, 2021). "Consistent with that, KAT2A and tyrosine kinase inhibitor combination could have significant clinical impact for the patients with abiraterone-resistant prostate cancer." (PMID 37296155, 2023). "Further supporting this hypothesis in the case of KAT2A is the observation that KAT2A-targeting shRNAs were specifically depleted (t test p = 0.06) in terms of incorporation into prostate cancer cell lines relative to all other cancer cell lines in the Achilles high-throughput screen." (PMID 28592290, 2017). "Intriguingly, SREBF1 has been report to interact with the epigenetic marks in cancer development, recruiting KAT2A/GCN5 to deposit the epigenetic mark H2A-K130ac on SREBF1, thereby reigniting lipogenesis and steroidogenesis in prostate cancer." (PMID 39962068, 2025). "Our approach has yielded 11 transcription factors that show strong cancer-specific transcriptional activation of targets, including the novel candidates KAT2A and TRIM28, alongside established drivers of prostate cancer MYC, ETS1, GABP and YY1." (PMID 28592290, 2017). "Of the highlighted genes without previously known roles in prostate cancer, we find it interesting to note that both KAT2A and TRIM28 have epigenetic remodelling functions." (PMID 28592290, 2017). "Amongst these sets, the novel candidates KAT2A, TRIM28 and HEY1 are particularly interesting, as they represent previously unknown putative drivers of prostate cancer." (PMID 28592290, 2017).
glioblastoma (3 papers, 2021 to 2025). The most malignant astrocytic tumor (WHO grade IV). "In human U251 glioblastoma (GBM) and HEK-293 cells, KAT2A depletion expectedly decreased the level of Ksuc in specific gene promoter sites; SIRT7 is recruited to DNA DSBs dependent on poly(ADP-ribose) polymerase 1 (PARP1), thereby promoting DSB repair and chromatin condensation." (PMID 38315203, 2024).
liver cancer (3 papers, 2022 to 2024). An epithelial or non-epithelial malignant neoplasm that arises from the liver. "Several studies have indicated that KAT2A is overexpression in multiple cancers compared with adjacent tissues, including liver cancer, colon adenocarcinoma tissues, and non-small cell lung cancer tissues." (PMID 39735192, 2024). "Multiple studies have revealed that KAT2A was highly expressed in a variety of cancers compared with adjacent tissues, such as liver cancer, colon adenocarcinoma tissues, and non-small cell lung cancer tissues." (PMID 36292703, 2022). "Among them, HDAC7, HDAC4, SIRT7, KAT2A, and HDAC11 were the top five most upregulated genes, indicating that the expression of deacetylation-related genes played a dominant role in liver cancer compared with acetylation-related genes." (PMID 36124029, 2022).
lung adenocarcinoma (3 papers, 2022 to 2025). A carcinoma that arises from the lung and is characterized by the presence of malignant glandular epithelial cells. "Among them, CRABP2, KAT2A, BIRC5, ABCC3, PLK1, IGHG1, and EPCAM were upregulated in lung adenocarcinoma samples, while FABP4 was downregulated in lung adenocarcinoma samples." (PMID 35909589, 2022).